OR10R2 (olfactory receptor family 10 subfamily R member 2)
Description:
Odorant receptor.
Synonyms: OR10R2Q; OR1-8
Gene: Protein-coding gene on chromosome 1 (158,472,220 to 158,480,936, forward strand). Ensembl gene ENSG00000198965.
Subcellular location: Cell membrane
Pathways (Reactome):
Sensory Perception: Expression and translocation of olfactory receptors
Genetic constraint (gnomAD): Loss-of-function variants: 1 observed, 1.86 expected, observed/expected ratio (o/e) 0.54, 90% interval 0.18 to 1.77. That is too few expected variants to judge how well the gene tolerates losing a copy. Missense variants: 396 observed, 371.63 expected, observed/expected ratio (o/e) 1.07, 90% interval 0.98 to 1.16. Synonymous variants: 154 observed, 143.74 expected, observed/expected ratio (o/e) 1.07, 90% interval 0.94 to 1.23.
Homologues: Orthologues: chimpanzee OR10R2 (99% identical), rabbit OR10R2 (90% identical), pig OR10R2 (89% identical). Paralogues in human: OR10T2 (57% identical), OR10K1 (55% identical), OR10K2 (53% identical), OR10Z1 (52% identical), OR10J1 (50% identical), OR10J3 (48% identical), OR10J5 (47% identical), OR1G1 (44% identical), OR1L3 (44% identical), OR1E1 (43% identical), OR1L1 (43% identical), OR2A25 (43% identical), and 116 more.
Diseases named in the same sentence as OR10R2 in open-access papers:
OR10R2 is named in the same sentence as 1 disease in open-access papers, as found by Europe PMC text mining. Sharing a sentence is not in itself a finding about the gene and the disease. The quoted sentences say what the papers report.
T-cell leukemia (1 paper, 2010). A malignant disease of the T-lymphocytes in the bone marrow, thymus, and/or blood. "Therefore, the possible regulatory role of Thy-ncR1 in OR10R2 gene expression was first examined in the thymus and in the Jurkat T-cell leukemia cell line." (PMID 21162727, 2010).